PSMD1 (proteasome 26S subunit, non-ATPase 1)
Diseases named in the same sentence as PSMD1 in open-access papers (continued):
Sharing a sentence is not in itself a finding about the gene and the disease.
tumor (continued). "Possible imbalances in regards to tumor site, nodal involvement, erythropoietin receptor or radiation may – if at all - favor patients with weak PSMD1-expression scores." (PMID 24593279, 2014). "PSMD1 expression was detected across all cell types, with the highest levels observed in HCC tumor cells." (PMID 41535254, 2026). "Using different experimental strategies of expressing shRNA, we found that PSMD1 depletion, either by expressing PSMD1 shRNA in an inducible manner or in a constitutive manner, robustly inhibited MDA‐MB‐231, and OVCAR8 xenograft tumor growth." (PMID 36934426, 2023). "In the present study, we identified a novel way in which PSMD1 and PSMD2 promote tumor cell proliferation—namely, via increasing cellular FA and lipid synthesis." (PMID 31703613, 2019). "Recent studies indicate that knockdown of PSMD1 and/or PSMD2 is able to suppress tumor cell proliferation." (PMID 31703613, 2019). "Briefly, the knockdown of PSMD1 and/or PSMD2 decreases the formation of cellular lipid droplets, the provider of the energy and membrane components for tumor cell proliferation." (PMID 31703613, 2019). "This study provides new insights into the PSMD1/PSMD2 regulatory mechanism in HCC cell proliferation and provides a potential novel therapeutic strategy for lipid-rich tumor." (PMID 31703613, 2019). "Our findings provide new insight into the regulatory roles of PSMD1 and PSMD2 in tumor cell proliferation via regulating lipid metabolism." (PMID 31703613, 2019). "We observed variable expression of PSMD1 in GC tissues, and positive correlation of PSMD1 expression with TNM stage in tumor tissues." (PMID 31413756, 2019). "The results indicated that high expression levels of PSMD1 and PSMD2 decrease the survival rate of LIHC, which corresponds to our study where PSMD1 and PSMD2 increased the LD content and promoted tumor cell proliferation." (PMID 31703613, 2019). "Therefore, as the important subunits of the 26S proteasome, PSMD1 and PSMD2 also regulate tumor cell growth." (PMID 31703613, 2019). "In the present study, we analyzed PSMD1 and PSMD3 mRNA and protein expression in cancerous tissue versus normal controls using data from The Cancer Genome Atlas (TCGA) and the Clinical Proteomic Tumor Analysis Consortium (CPTAC), comparing expression with overall survival." (PMID 34572038, 2021). "mRNA level analysis of PSMD1 expression in matched nontumoral and tumor tissues showed that PSMD1 was upregulated in the majority of GC tissues compared to their nontumoral counterparts (25/36; 69.4%), and PSMD1 protein levels were also significantly higher in tumor tissues." (PMID 31413756, 2019). "PSMD1 and PSMD2 could be potential therapeutic targets for this type of tumor." (PMID 31703613, 2019). "Kaplan-Meier estimates show that patients who underwent radiotherapy for macroscopic tumor and whose tumor cells exhibited weak or intermediate, as opposed to strong PSMD1 expression, had a decreased median overall survival probability (21.2 vs 28.8 vs 43.8 months, log-rank, p = 0.05)." (PMID 24593279, 2014). "As far as we know, no study has reported this regulatory function of PSMD1 and PSMD2 in tumor cells." (PMID 31703613, 2019). "However, the way in which PSMD1 and PSMD2 regulate tumor cell proliferation is not totally clear." (PMID 31703613, 2019).
neurodegenerative disease (1 paper, 2023). A disorder of the central nervous system characterized by gradual and progressive loss of neural tissue and neurologic function. "Considering the KEGG pathways, the most enriched terms are related to neurodegenerative diseases with the involvement of the same hubs Psmd1 and Psmd12." (PMID 37355705, 2023).
PSMD1 also shares sentences with these, for which no sentence is quoted: COVID-19 (241 papers); viral infection (40); influenza (10); colorectal cancer (6); adenocarcinoma (4); colon cancer (4); severe acute respiratory syndrome (4); thymic carcinoma (4); Autoimmunity (3); cervical cancer (3); hemorrhage (3); lung disease (3); malaria (3); melanoma (3); Obesity (3); Anxiety (2); cardiovascular disease (2); chronic myeloid leukaemia (2); Cirrhosis (2); cognitive decline (2); cognitive deficits (2); dengue (2); diabetes (2); endothelial dysfunction (2); Epstein-Barr virus infection (2); hematologic malignancies (2); Hypertension (2); infectious disease (2); metastatic colorectal cancer (2); Parkinson disease (2).
A further 69 diseases each share a sentence with PSMD1 in 2 papers or fewer.